RAN (RAN, member RAS oncogene family)
Description:
GTPase involved in nucleocytoplasmic transport, participating both to the import and the export from the nucleus of proteins and RNAs. Switches between a cytoplasmic GDP- and a nuclear GTP-bound state by nucleotide exchange and GTP hydrolysis. Nuclear import receptors such as importin beta bind their substrates only in the absence of GTP-bound RAN and release them upon direct interaction with GTP-bound RAN, while export receptors behave in the opposite way. Thereby, RAN controls cargo loading and release by transport receptors in the proper compartment and ensures the directionality of the transport. Interaction with RANBP1 induces a conformation change in the complex formed by XPO1 and RAN that triggers the release of the nuclear export signal of cargo proteins. RAN (GTP-bound form) triggers microtubule assembly at mitotic chromosomes and is required for normal mitotic spindle assembly and chromosome segregation. Required for normal progress through mitosis. The complex with BIRC5/survivin plays a role in mitotic spindle formation by serving as a physical scaffold to help deliver the RAN effector molecule TPX2 to microtubules. Acts as a negative regulator of the kinase activity of VRK1 and VRK2. Enhances AR-mediated transactivation. Transactivation decreases as the poly-Gln length within AR increases.
Synonyms: ARA24; TC4; Gsp1
Tractability: Small molecule: a structure with a bound ligand is known; it has a binding pocket of medium quality. PROTAC: UniProt records ubiquitination sites on it; ubiquitination databases record sites on it; its protein half-life has been measured; a small molecule that binds it is known.
Gene: Protein-coding gene on chromosome 12 (130,872,037 to 130,877,678, forward strand). Ensembl gene ENSG00000132341.
Subcellular location: Nucleus; Nucleus envelope; Cytoplasm, cytosol; Cytoplasm; Melanosome
Subcellular location (Human Protein Atlas): Nucleoplasm
Pathways (Reactome):
Disease: NEP/NS2 Interacts with the Cellular Export Machinery; Nuclear import of Rev protein; Rev-mediated nuclear export of HIV RNA
Gene expression (Transcription): MicroRNA (miRNA) biogenesis; Transcriptional regulation by small RNAs
Cell Cycle: Postmitotic nuclear pore complex (NPC) reformation
Metabolism: Regulation of cholesterol biosynthesis by SREBP (SREBF)
Metabolism of RNA: tRNA processing in the nucleus
Gene Ontology:
Molecular function: cadherin binding; G protein activity; GDP binding; GTP binding; GTPase activity; magnesium ion binding; pre-miRNA binding; protein binding; protein heterodimerization activity; RNA binding; chromatin binding; nuclear export signal receptor activity
Biological process: GTP metabolic process; mitotic sister chromatid segregation; positive regulation of protein import into nucleus; protein export from nucleus; protein import into nucleus; protein localization to nucleolus; ribosomal large subunit export from nucleus; ribosomal small subunit export from nucleus; snRNA import into nucleus; DNA metabolic process; mitotic cell cycle; mitotic spindle organization; pre-miRNA export from nucleus; ribosomal subunit export from nucleus; viral process; nucleocytoplasmic transport
Cellular component: centriole; chromatin; cytoplasm; extracellular exosome; Flemming body; melanosome; membrane; midbody; nuclear envelope; nucleolus; nucleoplasm; nucleus; protein-containing complex; recycling endosome; RNA nuclear export complex; cytosol; nuclear pore
Genetic constraint (gnomAD): Loss-of-function variants: 2 observed, 26.27 expected, observed/expected ratio (o/e) 0.0761, 90% interval 0.03 to 0.24. The synonymous counts are far from expectation, so gnomAD's model fits this gene poorly and the ratio says little. Missense variants: 56 observed, 270.04 expected, observed/expected ratio (o/e) 0.21, 90% interval 0.17 to 0.26. Synonymous variants: 132 observed, 95.92 expected, observed/expected ratio (o/e) 1.38, 90% interval 1.19 to 1.59.
Homologues: Orthologues: mouse Ran (100% identical), tropical clawed frog ran (98% identical), zebrafish ran (94% identical), rat Rasl2-9 (94% identical), Caenorhabditis elegans ran-1 (87% identical), Drosophila melanogaster Ran-like (61% identical).
Diseases named in the same sentence as RAN in open-access papers:
RAN is named in the same sentence as 95 diseases in open-access papers, as found by Europe PMC text mining. Sharing a sentence is not in itself a finding about the gene and the disease. The quoted sentences say what the papers report.
breast carcinoma (12 papers, 2009 to 2025). "Overexpression of RAN has been associated with increased cellular proliferation in breast cancer, while persistent STAT3 activation has long been implicated in psoriasis." (PMID 40959079, 2025). "RAN has been shown to be implicated in carcinomas, such as breast cancer and lung cancer, by regulating cell adhesion, migration and invasion." (PMID 31949483, 2020). "In breast cancer, pimozide has also been proven to promote apoptosis by inhibiting RAN GTPase and AKT and to inhibit epithelial-mesenchymal transition and cell migration." (PMID 34336684, 2021). "Already, there are nanoparticles treatments containing inhibitory peptides targeting RAN that have great potential in therapy of breast cancer." (PMID 33102517, 2020). "The largest difference (ca 10,000 fold) between the less aggressively (MCF-7, ZR-75) and more aggressively malignant (MDA MB 231, MDA MB 435S) human breast cancer cell lines is that due to RAN, the next is that due to osteopontin itself." (PMID 19192273, 2009). "The relatively non-invasive breast cancer cell line ZR-75 showed almost identical levels of low expression of RAN and OPN to those of the MCF-7 cell line." (PMID 19192273, 2009). "In breast cancer, when RAN GTPase was overexpressed, XPO5 level was also significantly increased." (PMID 31374978, 2019). "Some of the differentially expressed genes were then tested further by Real Time PCR for the relative level of their expressed mRNAs in a series of cell lines established from human breast cancer and the mRNA species which changes the most has been identified as RAN GTPase." (PMID 19192273, 2009). "In order to shed new lights into the molecular pathways affected by Pimozide, we show that Pimozide downregulated RAN GTPase and AKT at both protein and mRNA levels and inhibited the AKT signaling pathway in MDA-MB-231 breast cancer cells." (PMID 30405882, 2018). "The genotype frequencies of RAN rs14035 and XPO5 rs11077 in the control group of our study showed similar patterns to the results in the control groups of previous reports regarding lung cancer and breast cancer in Korea." (PMID 24769857, 2014).
neuroblastoma (11 papers, 2013 to 2024). Neuroblastoma (NB) is the most common solid, extracranial childhood tumor. "Other environmental factors, such as dietary habit, childhood exposure, and health situation, would help to provide further insight into the influence of RAN/RANBP2 polymorphisms on neuroblastoma risk." (PMID 29706609, 2018). "In all, here we demonstrate that common variants at the RAN/RANBP2 genes are associated with the risk of neuroblastoma in the Chinese children in a low-impact manner." (PMID 29706609, 2018). "The current study was the first investigation on the association of RAN/RANBP2 genes SNPs with neuroblastoma risk." (PMID 29706609, 2018). "In the current study, we performed the first investigation into the impact of SNPs in RAN/RANBP2 genes on the risk of neuroblastoma in Chinese Han children." (PMID 29706609, 2018). "Stratification analysis for the association between RAN gene genotypes and neuroblastoma susceptibility." (PMID 29706609, 2018). "Stratification analysis was further adopted to assess the effects of the RAN polymorphisms on neuroblastoma risk among different strata." (PMID 29706609, 2018). "We further investigated the combined effect of protective genotypes of RAN in neuroblastoma risk." (PMID 29706609, 2018). "Further studies are warranted to validate the weak impact of RAN/RANBP2 SNPs on neuroblastoma risk." (PMID 29706609, 2018). "Herein, for the first time we investigated whether RAN/RANBP2 SNPs could contribute to the risk of neuroblastoma in Chinese children." (PMID 29706609, 2018). "However, three protective RAN genotypes were observed to cumulatively reduce the risk of neuroblastoma." (PMID 29706609, 2018). "Given the unknown role of RAN/RANBP2 single nucleotide polymorphisms (SNPs) in neuroblastoma risk, we performed a multi-center case-control study in Chinese children to assess the association of the RAN/RANBP2 SNPs with neuroblastoma risk." (PMID 29706609, 2018). "LIN28B cooperates with RANBP2 to promote RAN expression and activity of RAN GTPase, thereby driving the oncogenesis of neuroblastoma." (PMID 33816306, 2021). "Subsequently, we demonstrated that LIN28B promotes the proliferation of neuroblastoma cells and defined RAN GTPase and Aurora kinase A (AURKA) as novel genes regulated by LIN28." (PMID 32923517, 2020). "Future larger-sample, functional studies are warranted to address the mechanism by which RAN/RANBP2 SNPs impacts tumorigenesis of neuroblastoma." (PMID 29706609, 2018). "In addition, the expression level of RAN was significantly altered in glioblastoma, pancreatic cancer, neuroblastoma, melanoma 35-40." (PMID 31949483, 2020). "Association of RAN and RANBP2 polymorphisms with neuroblastoma risk." (PMID 29706609, 2018). "However, the association of polymorphisms in the RAN/RANBP2 genes and neuroblastoma risk has yet to be elucidated." (PMID 29706609, 2018). "Our data revealed that the single RAN or RANBP2 gene polymorphism might not be strong enough to confer the neuroblastoma susceptibility in Chinese children." (PMID 29706609, 2018). "Immunoprecipitation proved that the RAN mRNA was a direct target of LIN28B, thus resulting in its upregulation and to an enhanced neuroblastoma cell growth." (PMID 37304235, 2023). "Overexpression of LIN28B in neuroblastoma increases the levels of RAN by directly binding RAN mRNA, and then RAN induces phosphorylation of threonine 288 of AURKA and increases AURKA enzymatic activity, ultimately facilitating neuroblastoma progression." (PMID 39510185, 2024). "This can occur either directly, since let-7 can target MYCN, or through activation of ras-related nuclear protein (RAN), which leads to increased transcription and phosphorylation of aurora kinase A (AURKA) and subsequent upregulation of MYCN, as shown in neuroblastoma." (PMID 32601913, 2020).
colorectal cancer (10 papers, 2004 to 2024). A primary or metastatic malignant neoplasm that affects the colon or rectum. "Recent study demonstrated that RAN rs14035 CT heterozygotes and T allele (CT + TT genotypes) had a lower colorectal cancer risk than individuals with other genotypes." (PMID 27611467, 2016). "In addition, the CT heterozygotes and T allele carriers of RAN rs14035 were found to have a lower risk of colorectal cancer." (PMID 36551880, 2022). "Another report, among Korean patients with colorectal cancer (CRC), indicated that the RAN*rs14035 variant was significantly correlated with a decreased risk of CRC (OR = 0.690; p-value = 0.016)." (PMID 37373948, 2023). "Alternatively, SIRT7 deacetylates RAS-related nuclear protein (RAN), an event that promotes nuclear accumulation of STAT3 and subsequent autophagic response, inhibiting proliferation and metastasis of colorectal cancer cells." (PMID 37676263, 2024). "For example, RANBP2, a binding protein of RAN (RAS related nuclear protein), a small GTPase of the RAS family, has been proposed as essential for survival of BRAF V600E mutant colorectal cancer cells and cells with a similar genomic signature." (PMID 36295658, 2022).
ovarian carcinoma (10 papers, 2014 to 2025). A malignant neoplasm originating from the surface ovarian epithelium. "RAN promotes membrane targeting and stabilization of RhoA to enhance ovarian cancer cell growth and invasiveness." (PMID 35836227, 2022). "In ovarian cancer, Lin28A enriched the mRNA of RAN and HSBP1, which was negatively correlated with survival and prognosis." (PMID 34868981, 2021). "Further dissection of the role of RAN, and its cellular functions, will need to be undertaken to fully understand their role in ovarian cancer." (PMID 24625450, 2014). "We have shown that high RAN expression strongly correlates with high-grade and poor patient survival in epithelial ovarian cancer." (PMID 24625450, 2014). "Therefore, RAN functions may be deregulated in ovarian carcinomas and RAN expression patterns may be used as a prognostic tool in patients with advanced EOC." (PMID 24625450, 2014). "However, multivariate analyses demonstrate a higher risk for patients expressing either RAN or TPX2 than for those expressing XPO7, suggesting a more significant contribution of RAN’s mitotic function to ovarian cancer progression than its nucleo-cytoplasmic function." (PMID 24625450, 2014). "The network of small-GTPases RAN proteins, of which RANBP1 is one of the main effectors, has also been demonstrated involved in the onset and progression of epithelial ovarian cancer (EOC)." (PMID 36672435, 2023). "In this study, we further confirmed that Lin28A can up-regulate the protein expression of RAN/HSBP1 to promote the stemness, the proliferation, the invasion and to inhibit the apoptosis of ovarian cancer cells." (PMID 32398961, 2020). "Then we detected the expression of Lin28A, RAN and HSBP1 in 47 ovarian benign tumor tissues and 96 ovarian malignant tumor tissues by immunohistochemical analysis." (PMID 32398961, 2020). "Moreover, RAN and HSBP1, when knocked down in ovarian cancer cells with high Lin28A expression, resulted in reduced malignancy characteristics, such as cell survival, invasion, and tumor growth in vivo, alongside increased apoptosis rates." (PMID 39150660, 2025).
hepatocellular carcinoma (9 papers, 2016 to 2025). A malignant tumor that arises from hepatocytes. "The goal of this study is to explore the association between XPO5*rs34324334 and RAN*rs14035 gene variants and susceptibility to hepatocellular carcinoma (HCC)." (PMID 37373948, 2023). "The Kaplan–Meier plotter database detected low and high mRNA expression levels of XPO5 and RAN among patients with hepatic carcinoma, respectively." (PMID 37373948, 2023). "The “five-gene” score (TAF9, RAMP3, HN1, KRT19, and RAN) was built to evaluate the genetic role in hepatic carcinoma and reported strong prognostic relevance." (PMID 35200757, 2022). "RAN was shown to interact with both CRM1 and PPARα in hepatoma cells." (PMID 40069732, 2025). "In hepatocellular carcinoma (HCC), a newly identified HBV-miRNA (HBV-miR-2) serves as a tumor-suppressor and an oncogenic miRNA by inhibiting Tripartite Motif Containing 35 (TRIM35) and targeting Ras-related nuclear protein (RAN)." (PMID 35889167, 2022). "Transmembrane protein 27 (CLTRN, also known as TMEM27) is a type Ia transmembrane, which can be regulated by the Nrf-1/RAN/DLD protein complex to deplete GSH and enhance the radiosensitivity of hepatocellular carcinoma (HCC) cells." (PMID 36176274, 2022).
pancreatic cancer (8 papers, 2011 to 2026). "RAN has been implicated in tumor progression and metastasis in various cancer subtypes, such as breast and pancreatic cancer, where it affects proliferation and apoptosis." (PMID 38666828, 2024). "RAN, a member of the RAS GTPase family, plays important roles in nucleocytoplasmic transport, and the overexpression of RAN in pancreatic cancer tissues is highly correlated with histological grade, suggesting that RAN plays a role in tumor progression." (PMID 35328637, 2022). "RAN promotes metastasis and invasion in pancreatic cancer by deregulating the expression of AR and CXCR4." (PMID 35626021, 2022). "RAN is also a GTPase, which regulates the nucleocytoplasmic import and export of proteins and RNAs, and reported to be involved in the metastasis of renal cell carcinoma and pancreatic cancer." (PMID 32346383, 2020). "Furthermore, depletion of RAN substantially inhibited the migration of metastatic pancreatic cancer cells and the capability of these cells to metastasize to the liver." (PMID 30671385, 2018).
lung carcinoma (7 papers, 2009 to 2024). "RanBP2 was identified as a new tumor suppressor in lung cancer and has been shown to play an essential role in cellular processes and protein stabilization, including the RAN protein." (PMID 39338204, 2024). "Similar contradictory effects were found in GEMIN4*rs781 [gastric (OR = 1.46) versus bladder (OR = 0.76) and lung cancer (OR = 0.79)] and RAN*rs14035 results [HCC (OR = 3.11) versus CRC (OR = 0.75)]." (PMID 36672288, 2023). "The elevated level of RAN was reported in different cancers such as ovarian, stomach, kidney, colon, and lung cancer." (PMID 33053689, 2020).
Alzheimer disease (6 papers, 2013 to 2024). A progressive, neurodegenerative disease characterized by loss of function and death of nerve cells in several areas of the brain leading to loss of cognitive function such as memory and language. "Disruption of the nucleocytoplasmic RAN gradient has been observed in neurodegenerative diseases, such as C9ORF72-ALS, Huntington’s disease, and Alzheimer’s disease." (PMID 33362237, 2020).
gastric cancer (5 papers, 2020 to 2024). A primary or metastatic malignant neoplasm involving the stomach. "Moreover, RAN is overexpressed in multiple tumors, including breast, renal and gastric cancer, and is associated with tumor progression, metastasis and poor patient survival." (PMID 36528654, 2022). "We then analyzed protein expression of RAN via IHC in 55 gastric cancer samples." (PMID 36528654, 2022). "The NEAT1/miR-130/IRF1 axis in gastric cancer, NEAT1/miR-24-3p/LRG1 axis in thoracic aortic aneurysm, NEAT1/miR-324-5p/RAN axis in retinoblastoma and NEAT1/miR-497-5p/PIK3R1 axis in renal tubular oxidative injury have been widely studied." (PMID 39546499, 2024). "Moreover, some studies have shown that miRNA-2 promoted carcinogenic activity by upregulating the expression of RAN in HCC cells; the high expression of HNRNPA1 promoted the invasion of gastric cancer cells; lncRNA CDKN2B-AS1 promoted the growth of HCC by regulating the let-7c-5p/NAP1L1 axis." (PMID 34426790, 2021).
amyotrophic lateral sclerosis (4 papers, 2019 to 2024). Amyotrophic lateral sclerosis (ALS) is a neurodegenerative disease characterized by progressive muscular paralysis reflecting degeneration of motor neurons in the primary motor cortex, corticospinal tracts, brainstem and spinal cord. "A post-transcriptional circuit comprising LSM12 and EPAC1 suppresses neurodegenerative pathologies in C9ORF72-associated amyotrophic lateral sclerosis by establishing the RAN gradient and sustaining nucleocytoplasmic transport." (PMID 33362237, 2020). "Finally, some DRiPs may also be generated via non‐canonical RAN translation of repeated sequences, whose expansion is associated with an increasing number of neurodegenerative diseases, including polyglutamine diseases, myotonic dystrophy type 1, and amyotrophic lateral sclerosis (ALS)." (PMID 31271238, 2019). "Here we analyzed whether different cellular stressors promote RAN translation of dipeptide repeats (DPRs) associated with the G4C2 hexanucleotide expansions in C9orf72, the most common genetic cause of amyotrophic lateral sclerosis (ALS) and frontotemporal dementia (FTD)." (PMID 30617154, 2019).